C20orf204 (chromosome 20 open reading frame 204)
Synonyms: PRR17; DKFZp434G015; FLJ27267; LINC00176; NCRNA00176
Gene: Protein-coding gene on chromosome 20 (64,034,344 to 64,039,962, forward strand). Ensembl gene ENSG00000196421.
Gene Ontology:
Cellular component: nucleus
Homologues: Orthologues: chimpanzee C20orf204 (100% identical), macaque C10H20orf204 (94% identical), pig C20orf204 (78% identical), dog C20orf204 (72% identical), rabbit C20orf204 (71% identical), guinea pig C20orf204 (66% identical), mouse Gm29797 (60% identical).
Diseases named in the same sentence as C20orf204 in open-access papers:
C20orf204 is named in the same sentence as 5 diseases in open-access papers, as found by Europe PMC text mining. Sharing a sentence is not in itself a finding about the gene and the disease. The quoted sentences say what the papers report.
hepatocellular carcinoma (5 papers, 2019 to 2021). A malignant tumor that arises from hepatocytes. "In this context we have previously found that C20orf204 (a splice variant of Linc00176) RNA contains a 189 amino acid (AA) long open reading frame (C20orf204-189AA) that is expressed predominantly in hepatocellular carcinoma (HCC)." (PMID 33731669, 2021). "Furthermore, we identified and determined that the functional small protein C20orf204-189AA encoded by long intergenic noncoding RNA Linc00176 that is expressed predominantly in hepatocellular carcinoma (HCC), enhances transcription of ribosomal RNAs and supports growth of HCC." (PMID 35008483, 2021).
tumor (6 papers, 2020 to 2024). "Previously, we have shown that C20orf204/Linc00176 RNA has a sponge function for tumor suppressor microRNAs, miR-9-5p and miR-185-5p." (PMID 33731669, 2021). "C20orf204 is specifically expressed in HCC and associated with tumor development." (PMID 36827259, 2023). "Nucleolin and C20orf204 mRNA levels in HCC are correlated with tumor differentiation grade and patient survival, suggesting that C20orf204-189AA is a cancer type-specific fine tuner in some HCC that presents itself for potential targeting therapy and cancer biomarker." (PMID 33731669, 2021). "Furthermore, C20orf204 and IFI27 were expressed in both the tumor and stromal regions, highlighting their broad relevance across these areas." (PMID 39135097, 2024).
cancer (3 papers, 2020 to 2024). A tumor composed of atypical neoplastic, often pleomorphic cells that invade other tissues. "These isoforms of lncRNAs may exhibit a long open reading frame like C20orf204 and may participate in cancer cell maintenance." (PMID 33731669, 2021). "The c20orf204-189AA encoded by lincRNA stabilizes nucleolin and promotes nucleosomal DNA transcription, and overexpression of c20orf204-189AA enhances HCC cell proliferation and nucleosomal DNA transcription, suggesting that this molecule is a cancer-specific micromodulators of HCC formation." (PMID 38622617, 2024). "C20orf204-189AA enhanced HCC proliferation and ribosomal RNA transcription and interacts with nucleolin and ribosomal RNA, indicating that this molecule is one of the cancer-specific fine tuners for HCC formation." (PMID 33731669, 2021).
C20orf204 also shares sentences with these, for which no sentence is quoted: ovarian carcinoma (3 papers); oesophageal cancer (1).